S100A7 (S100 calcium binding protein A7)
Diseases named in the same sentence as S100A7 in open-access papers (continued):
Sharing a sentence is not in itself a finding about the gene and the disease.
breast carcinoma (continued). "Altogether, this study identifies S1007/cPLA2 signaling as a promising target against metastatic breast cancers and demonstrates the efficacy of pharmacological inhibition of cPLA2 to improve the clinical outcome of S100A7-overexpressing breast cancer patients." (PMID 35135586, 2022). "Finally, we evaluated expression of S100P and S100A7 in gene expression data from 517 patients presenting with the various molecular subtypes of breast cancer compared to expression in 104 healthy volunteers." (PMID 35087607, 2022). "We discovered that S100A7 expression regulates the production of PGE2 in breast cancer cells." (PMID 35135586, 2022). "Interestingly, we sought to analyze the clinical significance of S100A7 and cPLA2 in relapse-free survival at 5 years in breast cancer patients treated with any chemotherapy using the ROC (receiver operating characteristics) plotter database." (PMID 35135586, 2022). "Therefore, the basal subtype is the only intrinsic molecular subtype of breast cancer, which showed an inverse pattern of expression for S100A7 and TLR4 as compared to normal samples." (PMID 33969603, 2022). "Moreover, CODEX analysis of orthotopic mouse mammary tumors demonstrated that inhibiting S100A7/cPLA2 signaling increased the abundance of proliferating as well as activated CD4+ and CD8+ TILs." (PMID 35135586, 2022). "Since its discovery, S100A7 has been shown to contribute to the progression of many cancers, including bladder, prostate, and skin cancers, and has been most studied in the context of breast cancer." (PMID 34360919, 2021). "S100A7 acts as a tumor suppressor in estrogen receptor-α–positive breast cancer." (PMID 33996571, 2021). "Especially, JAB1/S100A7 can enhance prosurvival pathway in breast cancer cells." (PMID 34244488, 2021). "Targeting the IGF-1/IGF-1R/S100A7 pathway may therefore represent a further useful approach for blocking disease progression in breast cancer patients with dysregulated IGF-1 signaling." (PMID 33557316, 2021). "Blockading of Stat3 inhibited cytokines-induced S100A7 expression in breast cancer cells." (PMID 31731716, 2019). "Compared to normal controls, MIAT was down-regulated in luminal B breast cancer tumor tissues which were inconsistent with our results, while S100A7, CCL5 and WT1-AS were up-regulated in luminal B breast cancer tumor tissues which were consistent with our results." (PMID 31795964, 2019). "In current study, S100A7 was the most significant up-regulated DEmRNAs in luminal B breast cancer tumor tissues, which may indicated that S100A7 exert momentous roles in luminal B breast cancer." (PMID 31795964, 2019). "OSM has previously been reported to induce S100A7 expression in breast cancer cells." (PMID 28629450, 2017). "We have shown that ASC-derived factors significantly promoted carcinoma cell proliferation and migration in breast carcinomas, and we have identified a potential oncogene, S100A7, that was markedly upregulated by an interaction between carcinoma cells and CAAs." (PMID 28629450, 2017). "S100A7 exerts different functions in breast cancer cells depending on different ER status." (PMID 28051137, 2017). "Furthermore, immunoreactivity of S100A7, the most upregulated gene in MCF7, after coculture with ASCs was evaluated for 150 breast cancer tissues to statistically analyze its association with clinicopathological parameters." (PMID 28629450, 2017). "Taken together, S100A7 expression at the site of breast carcinoma invasion into adipose stromal tissue could represent the status of carcinoma–ASC interaction in a breast tumor microenvironment." (PMID 28629450, 2017). "The more pronounced S100A7 immunoreactivity of breast carcinoma cells at the IF of adjacent adipose stromal tissues compared with that in the IT region suggests that upregulation of S100A7 could be promoted when carcinoma cells interact with breast ASCs." (PMID 28629450, 2017).
breast carcinoma (continued). "In this study, however, the clinicopathological significance of S100A7 in human breast cancer tissues supported the hypothesis that ASC-stimulated S100A7 could play important roles in tumorigenesis in a subset of patients with breast cancer." (PMID 28629450, 2017). "Furthermore RAGE/S100A7 signaling through paracrine and endocrine mechanisms in epithelial as well as TAMs plays an important role in linking inflammation to breast cancer development and metastasis." (PMID 27014721, 2016). "It has been noticed that S100A7 is upregulated in breast cancer cells." (PMID 25622979, 2015). "In this study, we used MDA-MB-231 and MCF7 as representative cellular models of ER− and ER+ breast cancers to analyze the mechanism by which S100A7 may differentially regulate cell proliferation." (PMID 25622979, 2015). "S100A7 (Psoriasin) is an inflammatory protein known to be upregulated in breast cancer." (PMID 25622979, 2015). "However, the role of S100A7 in breast cancer progression has been elusive, since both pro- and anti-proliferative roles have been reported in different types of breast cancer cells and animal models." (PMID 25622979, 2015). "However, the role of S100A7 in breast cancer has been elusive, since both pro- and anti-proliferative roles have been reported in different types of breast cancer cells and animal models." (PMID 25622979, 2015). "Interestingly, we noticed that, although S100A7 is overexpressed in both ER− and ER+ breast cancer patients, there is a significant mutual-exclusivity of S100A7 and ER expression in human breast tumors." (PMID 25622979, 2015). "Through bioinformatic analysis and in vitro assays, we found that miR-29b expression was reduced by S100A7 in ER− MDA-MB-231 and increased by S100A7 in ER+ MCF7 cells, which at least partly explained the different roles of S100A7 in regulating proliferation of different types of breast cancer cells." (PMID 25622979, 2015). "To date, the mechanism by which S100A7 differentially regulates ER− and ER+ breast cancer cell proliferation is unknown." (PMID 25622979, 2015). "In the present study, we show that S100A7 significantly downregulates the expression of miR-29b in Estrogen Receptor (ER)-positive breast cancer cells (represented by MCF7), and significantly upregulates miR-29b in ER-negative cells (represented by MDA-MB-231)." (PMID 25622979, 2015). "Thus, we confirmed that miR-29b is the determining factor of the differential effects of S100A7 in ER− and ER+ breast cancer cells." (PMID 25622979, 2015). "in the present study, we investigated whether S100A7 overexpression could be mechanistically associated with the up-regulation of NF-κB, VEGF and MMP-9, resulting in the promotion of breast cancer cell invasion and growth, and vice versa." (PMID 23618129, 2013). "S100A7 (Psoriasin) has also been shown to be induced by OSM in breast cancer cell lines." (PMID 24381786, 2013). "S100A7 signaling plays a critical role in the pathogenesis and progression of human breast cancers but the precise role and mechanism of S100A7 for tumor invasion remains unclear." (PMID 23618129, 2013). "This suggests that S100A7 may play an important role in the formation of osteolytic lesions and hence in the metastasis of breast cancer cells to bone." (PMID 18320059, 2008). "Many studies have showed that S100A7 had an increased expression in breast cancer." (PMID 18793447, 2008). "The overexpression of S100A7 was related to higher TNM stages of breast cancer and in estrogen receptor-negative invasive breast cancers, S100A7 expression was associated with poor outcome." (PMID 18793447, 2008). "Breast cancer iTME constituents possess the ability to reprogram tumor growth and distant metastasis; hence, a better understanding of the iTME would help in designing effective approaches for efficient targeting of S100A7-overexpressing metastatic breast cancers." (PMID 35135586, 2022).
breast carcinoma (continued). "Furthermore, our studies indicate that S100A7/cPLA2 could be used as novel prognostic marker and cPLA2 inhibitors as promising drugs against S100A7-overexpressing aggressive breast cancer." (PMID 35135586, 2022). "In addition, S100A7 may enhance breast cancer growth and metastasis through upregulating proinflammatory pathways and recruiting tumor-associated macrophages (TAMs)." (PMID 28212564, 2017). "Moreover, induction of oncostatin M was detected in cancer-stimulated ASCs, whereas the downstream S100A7 binding proteins/receptor for advanced glycation endproducts were significantly upregulated in correspondence with S100A7 expression in breast cancer cells after coculture with ASCs." (PMID 28629450, 2017). "The variance of inhibitory effects by S100A7 knockdown among breast cancer cells indicated that S100A7 may interact with several downstream proteins, such as c-Jun activation domain-binding protein 1 or Ran-binding protein M, to regulate carcinoma cell proliferation." (PMID 28629450, 2017). "Thus, it is suggested that RAGE might be activated in CAA-stimulated breast cancer cells via upregulation of S100A7 expression." (PMID 28629450, 2017). "Thus, the absence/presence of ER in breast cancer cells may lead to the differential regulations of NF-κB activation by S100A7 in MDA-MB-231 (ER−) and MCF7 (ER+) cells." (PMID 25622979, 2015). "Thus, it is suggested that miR-29b may be paired with S100A7 to serve as more accurate biomarkers for breast cancer diagnosis and prognosis." (PMID 25622979, 2015). "Hence, with the discovery of S100A7 - miR-29b regulatory route, miR-29b may be potential to serve as an alternative target for S100A7 overexpression in breast cancer treatment." (PMID 25622979, 2015). "In ER positive breast cancer cells, these alterations favor STAT3-dependant transcriptional activation of the S100A7 gene." (PMID 39830522, 2024). "Similar to SUM159 breast cancer cells, we discovered that treatment of LPS blocker (PMB) reduced the LPS‐mediated expression of S100A7 in S100A7‐overexpressing MDA‐MB‐231 cells." (PMID 33969603, 2022). "Additionally, KM plotter analysis also indicates that high expression of S100A7 with enriched macrophage population significantly associated with poor RFS probability for breast cancer patients, while high S100A7 expression with decreased macrophage showed non-significant clinical outcome." (PMID 35135586, 2022). "To further determine the clinical significance of S100A7 in regulating the PGE2 titer in breast cancer patients, we analyzed the titer of S100A7 and PGE2 and their correlation in breast cancer plasma samples." (PMID 35135586, 2022). "The result showed that the protein expression of TUBB3, MCM2, FN1, S100A7, and TFF1 was increased, and the protein expression of MYOC was downregulated in luminal A breast cancer, which was consistent with the result of RNA expression." (PMID 35692369, 2022). "Firstly, we analyzed the clinical significance of S100A7 and cPLA2 (PLA2G4A) in invasive breast cancer using publically available breast cancer datasets and human breast cancer tissue microarray (TMAs) by immunohistochemistry analysis." (PMID 35135586, 2022). "Differently, S100A7, S100A8 and S100A9 are co-amplified on chromosome 1q21.3 in breast cancer, have similar functions and cooperate with each other to induce target protein phosphorylation leading to tumor recurrence and chemoresistance." (PMID 35463335, 2022). "To evaluate the preclinical significance of cPLA2 inhibition in S100A7-overexpressing mammary tumors, we assayed the inhibitory effect of AACOCF3 on orthotopic and spontaneous breast cancer mouse models." (PMID 35135586, 2022). "In summary, our results indicate that S100A7 counteracts the expression of TLR4 in response to LPS treatment, which in turn activates the RAGE‐mediated downstream signaling in breast cancer cells." (PMID 33969603, 2022).
breast carcinoma (continued). "Extracellular expression of S100A7 is primarily associated with squamous cell cancer subtypes, namely lung cancer, head and neck cancer, cervical cancer, and bladder cancer, as well as with nonsquamous cancer subtypes, such as melanoma, breast cancer, and gastric cancer." (PMID 36613714, 2022). "To analyze the patient prognosis according to the expression of S100A7 and TLR4 based on tumor‐intrinsic features, we mined the KM plotter [breast cancer] database." (PMID 33969603, 2022). "We further tested the correlation between S100A7 and PLA2G4A gene expression in breast cancer patients using the SEEK database (Search-Based Exploration of Expression Compendium)." (PMID 35135586, 2022). "We also observed a significant positive correlation (Spearman’s rho correlation coefficient = 0.4) between circulating S100A7 and blood PGE2 in breast cancer patients." (PMID 35135586, 2022). "We also evaluated the prognostic significance of S100A7 and PLA2G4A alone or in combination and overall survival (OS) probability of immunomodulatory (IM) subtype of breast cancer patients using the Kaplan Meier (KM)-plotter [Breast cancer] tool (gene chip)." (PMID 35135586, 2022). "The protein expression results of TUBB3, MCM2, MYOC, FN1, S100A7, and TFF1 were consistent with the mRNA expression result COL10A1, LEP, PLIN1, PGM5-AS1, and TRHDE-AD1 were capable of discriminating luminal A breast cancer and normal controls." (PMID 35692369, 2022). "S100A7 is upregulated in several types of malignancies including oral squamous cell carcinoma (OSCC), nonsmall cell lung cancer (NSCLC), breast cancer (BRCA), and skin cutaneous melanoma, leading to tumor growth, premetastatic niche formation, and metastasis." (PMID 34323409, 2021). "In contrast, S100A7, S100A8 and S100A9, all of which are co-amplified on chromosome 1q21.3 in breast cancer, have similar functions and work together to induce target protein phosphorylation." (PMID 32929353, 2020). "We also demonstrated that S100A7 knockdown inhibited ASC-derived factor-induced cell proliferation and migration of various breast cancer cells." (PMID 28629450, 2017). "S100A7 can interact with HER2 signaling through distinct and specific phosphorylation of tyrosine resides of EGFR/HER2, Src and SHP2 in breast cancer cells." (PMID 28051137, 2017). "For example, previous studies have shown pro-tumorigenic and pro-metastatic role of ERBB2, WNT7b, S100A7, and MMP13 in breast cancer." (PMID 26669540, 2015). "In breast cancer (DCIS), both oncostatin M (OSM) and interleukin-6 (IL-6) have been proposed to regulate the expression and activity of S100A7 by regulating PI3K, STAT3 and Erk signaling." (PMID 20689826, 2010). "We also characterized EGFR's influence on S100A7 expression and its role in the EGF-induced metastasis and invasion of breast cancer cells." (PMID 18320059, 2008). "This study suggests that S100A7 plays an important role in EGFR-mediated signaling and osteoclast formation in breast cancer." (PMID 18320059, 2008). "Augmented mortality rate in breast cancer-afflicted patients with pre-existent metabolic disorders like obesity and diabetes, via impaired IGF-1 cues acting via S100A7/RAGE pathway, thereby promoting cancer-related angiogenesis in breast cancer micro-milieu, has been reported." (PMID 37970208, 2023). "Although S100A7 and cPLA2 individually are overexpressed in breast cancer, no study has been performed to show their correlation in metastatic breast cancer." (PMID 35135586, 2022). "Furthermore, S100A7 overexpression downregulated TLR4 and upregulated RAGE expression in breast cancer cells." (PMID 33969603, 2022). "Furthermore, we have also shown that expression of S100A7 is inversely correlated with TLR4 expression in breast cancer patients, especially in basal intrinsic subtype of breast cancer." (PMID 33969603, 2022). "Interestingly, a positive correlation between S100A7 and PGE2 levels was observed in breast cancer patient samples." (PMID 35135586, 2022).
breast carcinoma (continued). "Next, we evaluated the direct effect of LPS treatment on the expression of TLR4 in the presence or absence of S100A7 in breast cancer cells." (PMID 33969603, 2022). "Furthermore, we analyzed the correlation of S100A7 and PLA2G4A using the cBioPortal for cancer genomics database, which contains a large number of breast cancer samples of different subtypes." (PMID 35135586, 2022). "However, the microbiota‐derived LPS‐mediated regulation of S100A7 and TLR4 in breast cancer is yet unexplored." (PMID 33969603, 2022). "In the present study, S100A7 was overexpressed in breast carcinoma cells following interaction with hASC/3T3a cells but not with pre-hASC/pre-3T3 cells." (PMID 28629450, 2017). "In breast cancer, only S100A4, S100A7, and the heterodimer S100A8-S100A9 are extensively evaluated." (PMID 28051137, 2017). "To date, the mechanism by which S100A7 differentially regulates breast cancer cell proliferation is still not clear." (PMID 25622979, 2015). "Thus, we analyzed the effect of EGF on S100A7 expression in MCF-7 and MDA-MB-468 breast cancer cell lines." (PMID 18320059, 2008). "Breast cancer cells with high VEGF expression also have high IL-8 expression levels, which correlates with our data showing increased tumor growth and aggressiveness in S100A7-control cell lines as compared to S100A7-downregulated cell lines." (PMID 18320059, 2008). "Our in vivo findings concur with a previous study which reported that S100A7-downregulated tumors have reduced VEGF expression in vitro as compared to vector-transfected control cells, and that human breast cancer tissues with decreased S100A7 expression levels have reduced CD31 staining." (PMID 18320059, 2008). "In addition, a correlation was observed between high S100A7 expression and the angiogenic marker CD31 in samples derived from human breast cancer." (PMID 18320059, 2008). "Since epidermal growth factor receptor (EGFR), like S100A7, is often expressed in estrogen receptor-alpha-negative (ERα-) breast cancer, we set out to investigate the role of Jab1 in mediating EGFR signaling, another facet of the ERα- phenotype." (PMID 18534028, 2008). "Although up-regulation of mouse S100A7/psoriasin expression occurred in DMBA induced tumors compared to adjacent normal mammary gland tissue, expression levels showed a wide-scatter amongst the mammary tumors." (PMID 15717926, 2005). "Interestingly, S100A7 showed a significant negative correlation with TLR4 expression in the same cohort of breast cancer patient samples with their adjacent normal controls." (PMID 33969603, 2022). "S100A7 was also identified as an essential protein in breast cancer cells, especially in estrogen receptor α (ERα) negative cells, where the binding to RAGE leads to activation of extracellular signal-regulated kinase (ERK) and NF-κB signalling, resulting in tumour growth and enhanced metastasis." (PMID 32722137, 2020). "Though increased expression levels of S100A7 and RAGE have been frequently observed in ER− breast cancer, our results demonstrate that S100A7 and RAGE expression levels could also be induced in ER+ breast cancer cells by an interaction with ASCs." (PMID 28629450, 2017). "In brief, our results showed that the inhibition of S100A7/cPLA2 signaling could increase the infiltration of proliferating and activated CD4+ and CD8+ TILs in breast TME and may mount an enhanced anti-tumor immune response against aggressive metastatic breast cancer cells." (PMID 35135586, 2022). "Besides, MALAT1 was one of the top 10 up-regulated DElncRNAs in this study, and co-expressed with S100A7, which emphasized the critical role the MALAT1 in luminal B breast cancer and suggested that MALAT1 may involve in luminal B breast cancer by regulating S100A7." (PMID 31795964, 2019).